BMAL1 (basic helix-loop-helix ARNT like 1)
Diseases named in the same sentence as BMAL1 in open-access papers (continued):
Sharing a sentence is not in itself a finding about the gene and the disease.
tumor (continued). "Tumor growth rate in the nude mice injected with BMAL1 knockdown SUN-368 cells was remarkably faster than in those injected with control cells." (PMID 36439870, 2022). "According to our findings, the temporal patterns observed in lipid metabolism of control tumor cells (B-WT cells) were severely affected and mostly dampened after the disruption of Bmal1, a key component of the molecular clock (B-D cells)." (PMID 36183836, 2022). "We additionally demonstrated that the anti-tumor effect of BMAL1 was dependent on the down-regulation of GPAM." (PMID 36439870, 2022). "Recently, mice with defects in circadian rhythm (Bmal1-/-) were reported to show increased susceptibility to DSS-induced colitis and heightened tumour burden in AOM/DSS-mediated CAC." (PMID 36263033, 2022). "Although several studies have demonstrated that BMAL1 promotes tumor progression, many studies have revealed the tumor-suppressive role of BMAL1." (PMID 36357378, 2022). "To define the putative role of Bmal1 in tumor progression of the intestinal epithelium, we profiled gene expression using RNA sequencing (RNA-seq) from three independent biological replicates of late-passage WT, Bmal1−/−, Apc+/−, and Apc+/−;Bmal1−/− organoids." (PMID 35947664, 2022). "Further IHC analysis of 36 paired primary and metastatic HCC tissues showed that BMAL1 was markedly down-regulated in metastatic tumor tissues compared with primary HCC tissues." (PMID 36439870, 2022). "BMAL1 is characterized as a tumor suppressor, which is capable of suppressing cancer cell growth and invasiveness." (PMID 36066207, 2022). "To validate these findings in our GEMM, we performed gene expression analysis using Apc+/− and Apc+/−;Bmal1−/− tumor-derived organoids." (PMID 35947664, 2022). "BMAL1 inhibits tumor progression by suppressing glycerolipid metabolism through transcriptional inhibition of GPAM expressions in an EZH2 dependent way." (PMID 36439870, 2022). "The forced expression of BMAL1 resulted in lower tumor growth rates and weights in MHCC97H cells compared with controls." (PMID 36439870, 2022). "BMAL1 expression was also negatively associated with levels of LPA, PA, DAG and TAG in tumor tissues from 30 HCC patients." (PMID 36439870, 2022). "Microscopic images of intestinal tissue from both Apc+/− and Apc+/−;Bmal1−/− mice showed typical cytologic signs of neoplasia, with nucleomegaly and prominent nucleoli, hyperchromasia, and increased mitotic figures." (PMID 35947664, 2022). "Consistent with our results in HCC, BMAL1 has also been documented as a tumor repressor in numerous other kinds of cancers." (PMID 36439870, 2022). "Overall, our results as well as those of others collectively support the conclusion that BMAL1 functions as a novel tumor suppressor in human cancers." (PMID 36439870, 2022). "These time-specific drug actions were shown to occur in a tumor clock-dependent manner because genetic perturbation of BMAL1 in the cancer cells via RNAi knockdown or CRISPR genome editing abrogated the temporal response of the tumor to the drugs." (PMID 36430659, 2022). "In our study, decreased MITF and OPN4 (also higher BMAL1) gene expression is associated with a slower proliferation, higher antitumorigenic TME, and therefore, reduced tumor growth." (PMID 35562405, 2022). "In mice injected with circadian clock gene Bmal1 knocked‐down cells, a higher tumor growth rate was observed." (PMID 36066207, 2022). "A similar pattern of BMAL1 expression was demonstrated through immunohistochemistry (IHC) analysis of a large dataset of 217 HCC tumor tissues." (PMID 36439870, 2022). "All clock-related proteins were significantly more expressed in normal mucosa than in tumour tissues, except for BMAL1." (PMID 34440171, 2021). "Regarding Bmal and Clock, opposite roles for them have been described, with several evidences demonstrating that Bmal1 acts as a tumor suppressor, while Clock would be a tumor driver." (PMID 33535472, 2021).
tumor (continued). "RT-qPCR was used to quantitate the RNA expression of Bmal1 and miR-7239-3p in vitro, and Western blot was used to assess the expression of tumor-related proteins." (PMID 33528793, 2021). "The results showed that the expression of Bmal1 in tumor tissue from the GL261 + BV2 (M2) Exosomes group was reduced (P < 0.001), while the expression of miR-7239-3p was increased (P < 0.001)." (PMID 33528793, 2021). "In tumors, the induction of Reverba, and the Per and Cry genes occurred much faster than in the non-tumor tissues, within 6 h of the peak Bmal1 expression." (PMID 33495474, 2021). "While numerous studies have presented the activation of the PI3K/AKT axis as a key signaling pathway controlling EMT induction and tumor progression, BMAL1-KD favors, in the current study, the MET process of CRC cell lines." (PMID 34065633, 2021). "The Bmal1 gene is down-regulated in a variety of tumors, which inhibits tumor growth both in vivo and in vitro." (PMID 33528793, 2021). "Other regulators of circadian rhythms, such as BMAL1, can promote or repress angiogenesis, depending on the cancer type and probably also depending on the stage of tumor development." (PMID 34209857, 2021). "After the mice were sacrificed, the RNA expression levels of Bmal1 and miR-7239-3p in tumor tissue from each group were measured." (PMID 33528793, 2021). "The propagation (metastasis) to distant sites (M) at the moment of the disease diagnosis appeared in tumours with low levels of BMAL1 (p = 0.004) and PER2 (p = 0.037)." (PMID 34440171, 2021). "Studies revealed that BMAL1 is involved in the pathogenesis of human cancers, functioning either as tumor suppressor or oncogenic factor." (PMID 34065633, 2021). "The other central component of clock machinery, BMAL1, has notoriously been considered a tumor suppressor gene." (PMID 33114365, 2020). "Among others, BMAL1 gene was found to be sensitive to the pharmacological reversal of the epigenetic repression affirming its potential tumor suppressor effect." (PMID 32195174, 2020). "BMAL1 contributes to regulating cell-cycle progression, tumor cell apoptosis, and DNA-damage response and in homeostasis regulation by accelerating the development of tumors and influencing the response to cisplatin." (PMID 33364523, 2020). "It has been demonstrated that BMAL1 is down-regulated in particular types of cancer and its knockdown increased cell proliferation and tumor growth in cell culture and mice, respectively." (PMID 32195174, 2020). "This tumor promoting effect is likely due to decreased BMAL1 expression and consequent increased c-MYC expression." (PMID 33114365, 2020). "Downregulation of BMAL1 gene expression enhanced cell growth in vitro and promoted tumor growth in mice." (PMID 33364523, 2020). "Some studies have demonstrated that downregulation of BMAL1 gene expression promotes cancer cell proliferation, invasion, and tumor growth and decreases apoptosis induced by DNA damage." (PMID 33114365, 2020). "Together, the results suggested that tumor acidosis reduced BMAL1 via inhibition of transcription and decrease of protein stability." (PMID 32316196, 2020). "In the same study, the authors genetically manipulated the circadian genes Per2 (Per2m/m) and Bmal1 (Bmal1−/−) in whole-animal bodies, exhibiting the same previous effects describes, and so, pointing out their tumor-suppressive role in lung cancer." (PMID 33042011, 2020). "As a key component in the circadian clock machinery, Bmal1 has been recognized to play an important role in the sensitivity of anti-tumor drugs." (PMID 32522976, 2020). "(A) Bmal1 gene expression and protein levels in WT macrophages treated with control medium or increasing doses of B16-F10 tumor-conditioned medium (T-CM, diluted 1:3 or 1:1 with control medium) for 8 hr." (PMID 32396064, 2020). "In order to comprehend how the BMAL1 gene affects tumor growth and its response to cisplatin, a study examined the effect of knockdown of BMAL1 by RNAi." (PMID 33364523, 2020).
tumor (continued). "Since BMAL1 was reduced by tumor acidosis, we wanted to identify a biological mechanism to prevent the decrease of BMAL1 during tumor acidosis." (PMID 32316196, 2020). "How important is the O-GlcNAcylated YY1 suppression of Bmal1 to the function and circadian rhythm of tumour microenvironment cells?" (PMID 33375613, 2020). "In the current study, we show that inflammatory stimulants, including Ifn-γ/LPS and tumor-derived factors, control the expression of the circadian master regulator Bmal1 in the macrophages." (PMID 32396064, 2020). "PERK-induced miR-211 inhibition of Bmal1 and Clock in tumor cells is another mechanism that has been recently demonstrated where this pathway inhibits circadian rhythm oscillations and ongoing protein synthesis, thereby promoting tumor progression." (PMID 33267910, 2020). "We find that the molecular clock Bmal1 is induced by inflammatory stimulants, including Ifn-γ/lipopolysaccharide (M1) and tumor-conditioned medium, to maintain mitochondrial metabolism under metabolically stressed conditions in mouse macrophages." (PMID 32396064, 2020). "Under the circumstance that CLOCK and BMAL1 are lower expressed, the tumor microenvironment is in the state of “nighttime”." (PMID 31881010, 2019). "We detected that Bmal1 has a direct link with tumor invasion in the brain through interaction with Mdm2 and other cancer-related genes." (PMID 31523185, 2019). "For example, multiple studies have revealed lower expression of BMAL1 in tumor tissue compared to healthy adjacent tissues in patients with pancreatic cancer and pancreatic ductal adenocarcinoma, as well as colorectal cancers." (PMID 31151182, 2019). "In conclusion, our research proposes a novel insight into the role of CLOCK and BMAL1 in tumor cells." (PMID 30287810, 2018). "Patients with high miR-135b/low BMAL1/high YY1-expressing tumours presented with significantly shorter OS and PFS times and relatively unfavourable responses to GEM therapy." (PMID 29396463, 2018). "By directly targeting the 3′-UTR, miR-135b suppressed BMAL1 expression and thereby disturbed the entire molecular clockwork inside the exocrine pancreas, leading to impaired circadian control of tumour suppression." (PMID 29396463, 2018). "In each case, the levels of Bmal1 mRNA expression was stronger in normal tissue in comparison to tumour tissue from the same patient (p < 0.0005, n = 8)." (PMID 30348208, 2018). "To further investigate the roles of the circadian core protein CLOCK and BMAL1 in tumor cells, we performed immunofluorescence assays and found that both endogenous CLOCK (red) and BMAL1 (red) overlapped with RHOA (green), mainly in the cytoplasm." (PMID 30287810, 2018). "Considering that F-actin filament dynamics are involved in a variety of significant bioprocesses, our current research provides a new perspective on the roles of CLOCK and BMAL1 in tumor cells." (PMID 30287810, 2018). "Meanwhile, IHC analysis showed that BMAL1 was negatively associated with miR-135b expression and aggressive parameters of PC, whereas the YY1 level was positively related to pT stage and tumour differentiation." (PMID 29396463, 2018). "The Kaplan–Meier analysis revealed that patients with high miR-135b/low BMAL1/ high YY1-expressing tumours had significantly shorter overall survival (OS) times." (PMID 29396463, 2018). "In separate studies performed in lung cancer and glioma cells, knockdown of BMAL1 promoted cancer cell proliferation, invasion, and tumor growth, while its overexpression reduced cellular invasiveness." (PMID 29780357, 2018). "While HNF4α and BMAL1 are robustly co-expressed in normal hepatocytes, of significance is the distinct downregulation of BMAL1, which has been demonstrated to play tumor suppressive roles in HNF4α-positive HCC." (PMID 30341289, 2018).
tumor (continued). "Levels of Bmal1 messenger RNA (mRNA) were significantly altered in the tumours in comparison to normal epithelia." (PMID 30348208, 2018). "The CCAAT/enhancer binding protein alpha (C/EBPalpha) regulates the expression of PER2 and depletion of BMAL1 in unmethylated cells promotes tumor growth while its reintroduction in tumor cells slowed down growth in colony assays and nude mice." (PMID 28674522, 2017). "Knocking down the essential clock gene Bmal1 in B16 tumors prevented the effects of dexamethasone on tumor growth and cell cycle events." (PMID 28196531, 2017). "Overexpression of Bmal1 inhibits, whereas RNA interference of Bmal1 promotes tumor cell proliferation as well as cell invasion." (PMID 27602774, 2016). "The circadian rhythm molecule Period2 (Per2) plays a critical role as a tumor suppressor by controlling levels of BMAL1." (PMID 27285754, 2016). "BMAL1 was down-regulated in both neighbouring and tumour tissue compared to normal mucosa, while CLOCK was slightly up-regulated in neighbouring tissue and slightly down-regulated in tumour." (PMID 27465361, 2016). "Cytoplasmic BMAL1 staining was slightly stronger in the tumour and the neighbouring mucosal cells than in the normal, unrelated mucosa." (PMID 27465361, 2016). "In the nuclei, BMAL1 was significantly increased in neighbouring tissue, and also slightly increased in tumour tissue compared to normal mucosal cells." (PMID 27465361, 2016). "As a reduction in Bmal1 increases proliferation and cyclin D1 expression in both murine cells and tumours, as well as decreasing apoptosis." (PMID 25822259, 2015). "Core clock proteins interact with components of the cell cycle to rhythmically control cell-cycle genes, such as Wee1, Cyclin D1, C-myc and p21(Waf1/Cip1), and PERIODs and BMAL1 have been described as tumour suppressors." (PMID 24728990, 2014). "The core clock proteins PERIODs (and BMAL1 more recently) have been described as tumour suppressors, rhythmically controlling cell-cycle genes." (PMID 24728990, 2014). "Previous studies have shown that Bmal1 is downregulated in certain types of cancer and suppresses tumor growth in cell culture and animal models." (PMID 23563360, 2013). "Previous studies have shown that Bmal1 suppresses tumor growth in cell culture and animal models and is down-regulated in certain types of cancer." (PMID 23563360, 2013). "Testing of a large panel of tumor cell lines and animal tumor models would be needed to determine how universal the selectivity of BMAL1-mediated protective effects towards normal tissues is." (PMID 22249125, 2011). "Poor 5-FU therapeutic outcomes are found at high tumor MI levels at 10 and 22 HALO, at which time tumor nuclear BMAL1 is lower." (PMID 19688113, 2009). "Each movie depicts, in two dimensions, the circadian differences in tumor volume or the toxic therapeutic index of 5-FU and tumor nuclear BMAL-1 clock protein content." (PMID 19688113, 2009). "Supplementary Movie 1 shows the relationship of tumor size and tumor TS message, protein, enzyme activity, and tumor nuclear BMAL1 within the circadian cycle." (PMID 19688113, 2009). "Nuclear BMAL1 daily rhythm is shown in the bottom panel as a measure of the circadian clockwork in tumor cells." (PMID 19688113, 2009). "To directly investigate whether BMAL1 promotes the growth and survival of ccRCC cells, we measured clonogenicity in three cell lines derived from ccRCC tumor biopsies (786O, RCC4, and A498) in which we used shRNA to deplete the expression of endogenous BMAL1." (PMID 40595592, 2025).
tumor (continued). "Furthermore, previous studies have implicated BMAL1 and ALDOC in metabolic reprogramming and tumor progression, particularly under hypoxic conditions." (PMID 40535800, 2025). "Importantly, we confirmed through mechanistic studies that ALDH3A1 is a direct transcriptional target gene of BMAL1, thus establishing a new molecular bridge between core circadian regulation and reprogramming of tumor glucose metabolism." (PMID 41228459, 2025). "Accordingly, researchers have begun to investigate the links between circadian disruption and oncogenesis, such as the tumor-suppressor roles of BMAL1 and PER2 in lung tumor initiation and progression, and the induction of MYC by CLOCK and bHLH proteins, which facilitates neuroblastoma progression." (PMID 40700255, 2025). "The inhibitory effects of BMAL1 overexpression were potentiated by co-treatment with melatonin, indicating that melatonin’s anti-tumor effects are consistent with and may amplify the BMAL1-mediated suppression of glycolysis and proliferation." (PMID 41228459, 2025). "In NSCLC, where inflammation and immune modulation are predominant, recent studies demonstrate that restoring BMAL1 function could potentially reduce oxidative stress and support anti-tumor immunity, opening avenues for circadian-based therapies." (PMID 39812541, 2025). "Interestingly, the expression of exogenous p62 ΔNES resulted in substantial downregulation of BMAL1 protein levels and inhibited tumor cell growth both in RKO and SW480 cells, whereas WT p62 expression did not provide a comparable impact." (PMID 40638681, 2025). "This suggests that circadian rhythms could dramatically influence the effectiveness of HIF2α antagonists in ccRCC, either due to tumor-intrinsic expression of BMAL1 or other physiological rhythms." (PMID 40595592, 2025). "We also revealed that remodeling the nuclear accumulation of p62 may represent a potential strategy for targeting BMAL1 to suppress tumor cell growth." (PMID 40638681, 2025). "Other studies suggested depletion of core genes CLOCK and BMAL1 impairing tumor progression." (PMID 40565338, 2025). "Furthermore, pharmacological activation of BMAL1 using the agonist SR8278 recapitulates this anti-tumor effect and demonstrates significant synergy with melatonin." (PMID 41228459, 2025). "In summary, these results indicate that remodeling the nuclear accumulation of p62 may represent a potential strategy for targeting BMAL1 to suppress tumor cell growth." (PMID 40638681, 2025). "For example, FABP7 in GBM epigenetically reprograms to suppress immune-related gene expression while upregulating ferroptosis-resistance gene BMAL1, helping tumor cells evade immune clearance and ferroptosis, which demonstrates deep integration of metabolic regulation and epigenetics." (PMID 40717587, 2025). "Alternatively, the knockdown of the clock gene BMAL1 in carcinoma cells induces tumor growth when cells are injected subcutaneously, which may be mediated by the inhibition of apoptosis and reduction in the time that the cells remain in the G2/M phase." (PMID 41234239, 2025). "Moreover, the patients with high BMAL1 tumor expression also achieved significant clinical benefits from immune checkpoint inhibitors." (PMID 38834742, 2024). "Additionally, examination of tumor tissues from KITV558A/WT mice and KITV558A/WT/ZSWIM4−/− mice by qRT-PCR and western blot showed that loss of ZSWIM4 expression increases KIT and BMAL1 expression." (PMID 38951864, 2024). "Of note, tumour-promoting microglia were also found to influence the expression of clock proteins in GBM cells, mainly the downregulation of BMAL1 by tumour-promoting microglia exosomes carrying miR-7239-3p (microRNA-7239-3p) and concurrent upregulation of CLOCK32." (PMID 38378853, 2024).